OR5M3 (olfactory receptor family 5 subfamily M member 3)
Description:
Odorant receptor.
Synonyms: OR11-191
Tractability: Antibody: UniProt places it where antibodies can reach, with medium confidence; UniProt predicts a signal peptide or a membrane-spanning region; its Gene Ontology location is reachable by antibodies, with medium confidence.
Gene: Protein-coding gene on chromosome 11 (56,469,274 to 56,473,352, reverse strand). Ensembl gene ENSG00000174937.
Subcellular location: Cell membrane
Pathways (Reactome):
Sensory Perception: Expression and translocation of olfactory receptors
Gene Ontology:
Molecular function: olfactory receptor activity; G protein-coupled receptor activity
Biological process: G protein-coupled receptor signaling pathway; sensory perception of smell; detection of chemical stimulus involved in sensory perception of smell
Cellular component: plasma membrane; membrane
Genetic constraint (gnomAD): Loss-of-function variants: 0 observed, 0.4 expected, observed/expected ratio (o/e) 0, 90% interval 0 to 1.85. That is too few expected variants to judge how well the gene tolerates losing a copy. Missense variants: 334 observed, 312.07 expected, observed/expected ratio (o/e) 1.07, 90% interval 0.98 to 1.17. Synonymous variants: 114 observed, 107.39 expected, observed/expected ratio (o/e) 1.06, 90% interval 0.91 to 1.24.
Homologues: Orthologues: macaque OR5M3 (94% identical), mouse Or5m3 (92% identical), rat Or5m3 (92% identical), dog OR5M3 (91% identical), mouse Or5m3b (90% identical), rabbit OR5M3 (89% identical), rat Or5m3b (89% identical), guinea pig OR5M3 (80% identical). Paralogues in human: OR5M9 (77% identical), OR5M8 (70% identical), OR5M10 (59% identical), OR5M1 (58% identical), OR5M11 (57% identical), OR5B12 (51% identical), OR5B21 (51% identical), OR5F1 (51% identical), OR5I1 (51% identical), OR5AP2 (50% identical), OR8K3 (50% identical), OR8D1 (50% identical), and 84 more.
Diseases named in the same sentence as OR5M3 in open-access papers:
OR5M3 is named in the same sentence as 2 diseases in open-access papers, as found by Europe PMC text mining. Sharing a sentence is not in itself a finding about the gene and the disease.
OR5M3 shares sentences with these, for which no sentence is quoted: prostate carcinoma (1 paper); tumour (1).